SLC7A11 (solute carrier family 7 member 11)
Diseases named in the same sentence as SLC7A11 in open-access papers (continued):
Sharing a sentence is not in itself a finding about the gene and the disease.
cancer (continued). "Other studies have also identified a role of SLC7A11 in regulating glutamine dependency or sensitivity to glutaminase inhibition in cancer cells." (PMID 29764521, 2018). "We next asked if xCT/SLC7A11 expression influences cystine-induced glutamine anaplerosis across other human cancer cell lines." (PMID 28826492, 2017). "This term is plotted against SLC7A11 mRNA expression data obtained from the cancer cell line encyclopedia (CCLE)." (PMID 28826492, 2017). "For each cancer type, we categorized 15–20 cancer cell lines as high and low SLC7A11 expressing and performed gene set enrichment analysis between these two groups." (PMID 28429737, 2017). "Similar to our findings, depletion of xCT/SLC7A11 improves cancer cell viability after glucose withdrawal through conservation of intracellular glutamate levels to maintain mitochondrial respiration." (PMID 28967864, 2017). "In that study, the combination of low miRNA-27a and high SLC7A11 was also observed in cancer tissues, but in a relatively low fraction of cases." (PMID 28767070, 2017). "Production of GSH as well as UDP-glucuronate was elevated in HCC cells expressing phospho-mimetic p62, and expression of Mrps and Slc7a11/xCT was markedly induced in these cells, suggesting that these cells would be tolerant to anti-cancer drugs." (PMID 27345495, 2016). "Xc- consists of the light-chain subunit xCT (SLC7A11) and a heavy-chain subunit (4F2hc/SLC3A2).11 xCT expression is increased in several cancers, and is associated with drug resistance and poor survival." (PMID 27421095, 2016). "Targeting disulfidptosis may offer a novel therapeutic strategy that exploits the metabolic vulnerabilities of cancer cells, potentially leading to more effective treatments that selectively induce cell death in SLC7A11-overexpressing tumors." (PMID 41346703, 2026). "Targeting SLC7A11 or GPX4 can sensitize radioresistant cancer cells to ferroptosis." (PMID 41596341, 2026). "Disulfidptosis—a regulated cell death caused by disulfide stress under glucose starvation and high SLC7A11—offers a potential cancer vulnerability, but its regulatory landscape and therapeutic tractability remain unclear." (PMID 41346703, 2026). "Through comparisons between glucose deprivation and normal samples and analysis with SLC7A11 expression and actin protein levels, we confirmed that these metrics reliably captured disulfidptosis vulnerability and showed promise in stratifying cancer types." (PMID 41346703, 2026). "For example, cancer cells may be more sensitive to ferroptosis, so quercetin induces ferroptosis by inhibiting SLC7A11." (PMID 40552277, 2025). "However, cancer cells can develop resistance by upregulating ferroptosis defense mechanisms, such as SLC7A11 and GPX4, to promote survival during radiotherapy." (PMID 41213903, 2025). "To answer the question whether POLR2A participates in the USP10‐medidated transcriptional activation of SLC7A11 and inhibition of cancer ferroptosis, we knocked down the expression of POLR2A in USP10‐overexpressed Cal27 cells." (PMID 40605431, 2025). "Thus, SLC7A11 is a key target in the regulation of ferroptosis, and the effect of reduced levels on cancer varies by type and microenvironment." (PMID 40438588, 2025). "Furthermore, specific demethylation of GATA3 and KDM6B transcripts can increase the expression of SLC7A11, leading to a decrease erastin sensitivity of cancer cells." (PMID 39800682, 2025). "Cancer cells may evade disulfidptosis via increased NADPH production or reduced SLC7A11, addressable by inhibiting compensatory metabolic routes." (PMID 41185600, 2025).
cancer (continued). "The reduced expression of SLC7A11 offers a potential target for cancer treatment, as it could be a useful biomarker for evaluating CSCs' response to ferroptosis-inducing therapies." (PMID 40821110, 2025). "Moreover, both in vitro and in vivo data suggest that METTL3/SLC7A11 is involved in m6A regulated growth and erastin sensitivity of cancer cells." (PMID 39800682, 2025). "SLC7A11-mediated GSH synthesis is essential for cancer cell survival and antioxidant defense." (PMID 40012016, 2025). "By elucidating the relationship between SLC7A11 expression and cancer hallmarks such as proliferation, migration, invasion, and ferroptosis, we propose that targeting this gene may serve as an impactful strategy in the fight against NSCLC." (PMID 41030277, 2025). "The previous discussion highlighted the crucial role of disulphide stress in inducing cell death in SLC7A11‐high cancer cells under glucose starvation conditions, characterized by excessive intracellular accumulation of disulphide molecules and NADPH depletion." (PMID 39354653, 2025). "Additionally, radiation has been shown to downregulate the expression of SLC7A11 in cancer cells in an ATM-dependent manner, leading to a reduction of cystine uptake and GSH synthesis, ultimately inducing ferroptosis in cancer cells." (PMID 40482348, 2025). "Due to the heightened sensitivity of HNC cells to disulfidptosis, the utilization of agents that induce disulfidptosis, along with the upregulation of related genes like SLC7A11, could enhance the vulnerability of these cancer cells to this form of cell death." (PMID 41185600, 2025). "Notably, cancer immunotherapy has shown the most promise in patients exhibiting low SLC7A11 expression." (PMID 39820491, 2025). "Moreover, genome-wide CRISPR screening of SLC7A11high cancer cells identified that, in addition to the expected XC-system (SLC7A3 and SLC7A11), NCKAP1 (Nck-associated protein 1) also plays a role in promoting disulfidptosis." (PMID 40012016, 2025). "Recent studies suggest that inhibiting glucose transporters (GLUTs) may be an effective strategy for inducing disulfidptosis in SLC7A11 high expression tumors, which are common in many human cancers." (PMID 39949740, 2025). "In the pan-cancer analyses, SLC7A11 was highly expressed in solid tumors, with its upregulation associated with worse prognosis, suggesting that it may serve as a novel prognostic biomarker." (PMID 40978058, 2025). "Several studies in recent years have extensively investigated the function of the disulfidoptosis-related SLC7A11 gene in cancer, but the role of its partner protein, SLC3A2, remains unknown unclear in NPC." (PMID 39926285, 2025). "Furthermore, gene interactions between cuproptosis regulators (e.g., FDX1, DLAT) and ferroptosis regulators (e.g., GPX4, SLC7A11) emphasize their interaction, highlighting potential therapeutic strategies that target mitochondrial vulnerabilities in cancers." (PMID 39949740, 2025). "Therefore, selectively inducing ferroptosis in CSCs through targeting SLC7A11 presents a promising novel approach for cancer therapy." (PMID 40821110, 2025). "However, subsequent functional analysis revealed that instead of promoting survival, SLC7A11 actually facilitates cell death in glucose‐starved cancer cells." (PMID 39354653, 2025). "Because cancer cells had a robust defense against oxidative stress that heavily relied on the transport of extracellular cysteine, SLC7A11 has been shown to be significantly upregulated in multiple cancer types, such as ovarian, hepatocellular, and colorectal cancers." (PMID 40478904, 2025). "In addition, there are currently some drugs on the market that act as ferroptosis inducers (such as Sulfasalazine, a clinically used drug for the treatment of chronic inflammatory diseases, which can target SLC7A11 to induce ferroptosis in cancer cells)." (PMID 40821694, 2025).
cancer (continued). "This confirmed that GATA3 positively regulated the transcription of SLC7A11 in cancer cells." (PMID 39800682, 2025). "High SLC7A11 expressed cancer cells show a glucose dependency to survive." (PMID 39820491, 2025). "Consequently, SLC7A11‐high cancer cells exhibit a heightened reliance on glucose for the provision of essential NADPH required to sustain efficient conversion of cystine into cysteine." (PMID 39354653, 2025). "This leads to a prevalent therapeutic concept: targeting SLC7A11 for cancer treatment." (PMID 39569390, 2025). "Recent research has underscored the potential benefits of targeting SLC7A11 in cancer treatment." (PMID 40535572, 2025). "Interestingly, while cancer cells with low SLC7A11 levels also undergo cell death under glucose deprivation, this form of death appears to be associated with apoptosis." (PMID 40012016, 2025). "Emerging evidence indicates that inhibiting SLC7A11 can increase the sensitivity of cancer cells to ferroptosis and other cell death forms, which may help to overcome therapeutic resistance." (PMID 40535572, 2025). "Notably, the overexpression of SLC7A11 in a range of human cancers correlates with poorer prognosis, further indicating its importance in oncogenic processes." (PMID 39569390, 2025). "In addition to these methods, drug induction experiments using glucose transporter inhibitors, such as BAY-876 and KL-11743, have demonstrated the ability to induce disulfidptosis in SLC7A11-overexpressing cancer cells." (PMID 40691135, 2025). "Interventions that aim to modify SLC7A11 activity could lead to innovative strategies to improve treatment effectiveness and address resistance mechanisms in cancer therapies, as well as help in reducing neurodegeneration." (PMID 40535572, 2025). "Finally, inhibition of the HIF-1α/SLC7A11 pathway blocks the Warburg effect and iron metabolism imbalance, inducing ferroptosis in cancer cells." (PMID 40584613, 2025). "Consequently, when deprived of glucose and NADPH, SLC7A11‐high cancer cells experience an abnormal accumulation of intracellular cystine and other disulphide molecules induced by NADPH depletion, leading to disulphide stress and subsequent rapid cell death." (PMID 39354653, 2025). "The lncRNA FERRIN, which is produced under conditions of glutamine starvation induced by the transcription factor ATF4, interacts with the RNA-binding protein hnRNPK, thereby promoting its binding to and stabilizing SLC7A11, and consequently promoting the proliferation of cancer cells." (PMID 40598593, 2025). "SLC7A11 is overexpressed in several cancers, including PCa, and may play a key role in disulfidptosis regulation." (PMID 41330917, 2025). "Therefore, cancer cells predominantly import cystine through SLC7A11, where it is subsequently reduced to cysteine in the cytoplasm." (PMID 40012016, 2025). "Importantly, glucose transporter inhibitors can induce disulfidptosis and suppress tumor growth in SLC7A11-high cancers." (PMID 40722814, 2025). "Research has demonstrated that upregulated SLC7A11 is common in human cancers, but the effect of disulfidptosis on GC remains unclear." (PMID 40427051, 2025). "Currently, the ferroptosis pathway is acquiring relevance for its impact on patients’ survival, ALB (included in our list) is especially reported as a prognostic factor, and the induction of ferroptosis by SLC7A11 targeting sensitizes BRCA-mutated and PARPi resistant cancer." (PMID 40136510, 2025). "In recent years, there has been significant research progress on the function of SLC7A11 in cancer." (PMID 39926285, 2025). "Existing studies suggest that SLC7A11 is a potential cancer therapeutic target." (PMID 40855044, 2025). "The ability of DhL to leverage elevated ROS levels in cancer cells, coupled with the potential of DhL for targeted therapy against cancers that overexpress antioxidant molecules such as SLC7A11, positions DhL as a promising candidate for further preclinical development." (PMID 40297144, 2025).
cancer (continued). "MLL4 is often mutated in human cancers, and its deficiency can result in decreased expression of pro-ferroptosis genes, including ALOX12, ALOX12B, and ALOXE3, as well as increased expression of anti-ferroptosis proteins such as SLC7A11 and GPX4." (PMID 41514908, 2025). "The interaction between SLC7A11 and various metabolic pathways highlights its critical role in cancer metabolism, positioning it as a promising target for therapeutic strategies designed to disrupt the metabolic adaptations that cancer cells undergo." (PMID 40535572, 2025). "Additionally, SLC7A11 not only facilitates cystine uptake but also exports glutamate, making SLC7A11high cancer cells highly dependent on glutamate produced from glutamine metabolism in the mitochondria." (PMID 40012016, 2025). "Hence, SLC7A11 is found to be upregulated in different types of human cancer, and its elevated expression can inhibit cellular ferroptosis, consequently leading to unfavorable prognostic outcomes for patients." (PMID 41210681, 2025). "Subsequent studies supported an alternative model suggesting that the glucose‐dependent phenotype observed in SLC7A11‐high cancer cells is more closely associated with SLC7A11‐mediated cystine uptake rather than glutamate export." (PMID 39354653, 2025). "Furthermore, inhibiting SLC7A11 not only reduces cellular antioxidant defenses but also sensitizes cancer cells to ferroptosis." (PMID 41030277, 2025). "Likewise, under hypoxic conditions, KDM4A SUMOylation induces SLC7A11 upregulation, enabling cancer cells to evade ferroptosis." (PMID 41439026, 2025). "Therefore, the regulatory pathway of SLC7A11 by the ERO1α/IL-6/STAT3 axis presents in human cancer cells with hyperactivated mTORC1 signaling." (PMID 38610018, 2024). "SLC7A11 serves as an important importer of cysteine for glutathione biosynthesis and antioxidant defense, and its overexpression is observed in various human cancers." (PMID 38831301, 2024). "This approach could potentially trigger synthetic lethal cell death specifically in cell lines that overexpress SLC7A11 and are thus sensitized to glucose deprivation, offering a promising avenue for targeted cancer therapies." (PMID 39040097, 2024). "Consequently, SLC7A11-high cancer cells exhibiting substantial cystine uptake and reduction become highly reliant on glucose to provide the necessary NADPH and maintain the swift conversion of cystine to cysteine." (PMID 38428031, 2024). "However, the correlation between the expression of ACSL4 and SLC7A11 in sera and cancer patients’ prognoses is still less explored in publications and remains controversial in several diseases." (PMID 39335604, 2024). "Since SLC7A11 expression is upregulated in several types of human cancers, it could be an important therapeutic target for cancer treatment." (PMID 38203758, 2024). "A substantial body of previous research has emphasized the importance of transcriptional activity associated with SLC7A11 in the process of ferroptosis; however, our understanding of how SLC7A11 maintains stability in human cancers remains limited beyond its transcriptional regulation." (PMID 38650929, 2024). "SLC7A11 has been shown to promote drug resistance, chemo-, and radioresistance in various cancers." (PMID 39029955, 2024). "Thus, the cystine/glutamate antitransporter xCT (encoded by the gene SLC7A11 and subunit gene SLC3A2) is highly expressed on the cell membrane in many cancer types." (PMID 39061847, 2024). "SLC7A11 is a key factor in the regulation of ferroptosis and cancer development." (PMID 39437660, 2024). "However, studies have found that high levels of SLC7A11 enhance the glucose dependence of cancer cells, exposing a potential vulnerability in cancer cell metabolism." (PMID 38739940, 2024). "In fact, additional studies reported that SLC7A11 was overexpressed in cancer, including lung AdC." (PMID 39769017, 2024).
cancer (continued). "This suggests that ferroptosis plays a crucial role in T cell-mediated antitumor activity, and targeting SLC7A11 in conjunction with ICIs could be a promising cancer treatment strategy." (PMID 38322268, 2024). "Notably, the inhibition of glucose transporters leads to robust cell death in SLC7A11-high cancer cells, and this process is potentially mediated by the disulfidptosis mechanism." (PMID 38428031, 2024). "Significant antitumor effects obtained by targeting the SLC7A11-GSH axis have been observed in various types of human cancers, and accumulated studies have shown that the induction of ferroptosis could reverse drug resistance." (PMID 39061826, 2024). "Furthermore, CD44 has been identified as capable of interacting with and stabilizing SLC7A11 on the membrane of cancer cells." (PMID 39040097, 2024). "As a critical regulator of ferroptosis, SLC7A11 could promote cancer progression partly through suppressing ferroptosis." (PMID 38605214, 2024). "This could be attributed to the high expression of SLC7A11, which could promote the proliferation and metastasis of cancer cells." (PMID 38886311, 2024). "Cancer cells upregulate SLC7A11 to manage elevated ROS levels." (PMID 39595619, 2024). "However, in cancer cells with high SLC7A11 expression, the low solubility and potential toxicity of intracellular cystine lead to accelerated reduction to the more soluble cysteine, consuming significant amounts of intracellular NADPH." (PMID 38831301, 2024). "Most cancer cells uptake extracellular cystine via the cystine transporter protein system Xc- (composed of the catalytic subunit SLC7A11 and the chaperone subunit SLC3A2) and subsequently utilize intracellular NADPH to reduce cystine to cysteine for cellular utilization." (PMID 38831301, 2024). "Thus, CEBPG favors cancer progression by inhibiting ferroptosis through an increase in SLC7A11 expression." (PMID 38203758, 2024). "Interestingly, SLC7A11 expression in cancer cells is induced by stress-inducible transcription factors, ATF4 and Nrf2, following glucose starvation." (PMID 38705513, 2024). "SLC7A11 has also a potential role in chemo-resistance by cancer cells." (PMID 38705513, 2024). "Indeed, preclinical investigations have demonstrated that, compared to their SLC7A11-low counterparts, SLC7A11-high cancer cells and tumors manifest heightened sensitivity to inhibitors of glucose transporters (GLUTs)." (PMID 38428031, 2024). "Consequently, cancer cells overexpressing SLC7A11 develop a heightened dependency on both the glucose and pentose phosphate pathways for their survival and proliferation." (PMID 39040097, 2024). "Moreover, in cancer cells, cystine uptake via SLC7A11 is crucial for maintaining the redox balance through GSH synthesis." (PMID 38739940, 2024). "Inhibiting this oncogenic pathway could potentially serve as an effective therapeutic approach for preventing SLC7A11-mediated metastasis of malignant tumors." (PMID 39807126, 2024). "This phenomenon significantly enhances our comprehension of post-translational regulatory mechanisms governing SLC7A11 function and underscores the importance of lncRNA involvement in SLC7A11-mediated metabolic reprogramming and iron-induced cell death in cancer." (PMID 38650929, 2024). "This could be due to the high expression of SLC7A11, which enhances the metabolic activity of cancer cells, thus conferring resistance to the toxic effects of certain chemotherapeutic drugs." (PMID 38886311, 2024).